YAP1 (Yes1 associated transcriptional regulator)
Diseases named in the same sentence as YAP1 in open-access papers (continued):
Sharing a sentence is not in itself a finding about the gene and the disease.
cutaneous melanoma (12 papers, 2018 to 2025). A primary melanoma arising from atypical melanocytes in the skin. "YAP1 expression was positively associated with PD-L1 expression in samples of cutaneous melanoma, creating an escape for destruction by CD8+ T cells." (PMID 33798262, 2021). "Gαq has been linked to YAP1 activation in non-cutaneous melanoma models." (PMID 40500450, 2025). "Our data also implicate TAZ as the major co-activator of TEADs in cutaneous melanoma, but the inhibitors developed hold therapeutic potential for targeting YAP1 and/or TAZ-TEAD signaling in other cancers." (PMID 41193428, 2025). "Increased YAP1 was associated with lower expression of CD8, HLA class I molecules, and TAP1 in cutaneous melanoma tissue, similarly pointing toward decreased immune recognition." (PMID 33798262, 2021). "In conclusion, the LTBP4-TGFβ1-Hippo-YAP1 axis is a critical pathway for the progression of skin melanoma." (PMID 35252214, 2021). "Recent evidence also suggests a functional relationship between YAP and Wnt5a in skin melanoma and pancreatic adenocarcinoma, two cancer types where a moderate correlation between YAP1 and WNT5A expression is observed." (PMID 33643710, 2021). "Similar to these findings in cutaneous melanoma, upregulation of the YAP1 pathway was found in UM models after MEK-inhibition." (PMID 33798262, 2021). "We have previously identified genetic variants of Hippo pathway genes (YAP1 rs11225163, TEAD1 rs7944031 and TEAD4 rs1990330) and revealed that Hippo effector TAZ significantly associated with unfavorable survival in cutaneous melanoma and primary OSCC." (PMID 30459528, 2018). "YAP1 expression was detected in cutaneous melanoma cell lines lacking a GNAQ/11 mutation (but harboring BRAF or NRAS mutations instead), and in human cutaneous melanoma tissue where a high expression was related to worse survival." (PMID 33798262, 2021). "Therefore, LTBP4 regulates the progression of skin melanoma via the TGFβ1/Hippo/YAP1 signaling pathway." (PMID 35252214, 2021). "For example, Hippo pathway genes YAP1, TEAD1, and TEAD4 may jointly modulate the survival of cutaneous melanoma patients." (PMID 35739490, 2022). "In human cutaneous melanoma, GRPR levels correlated with YAP1 activation scores, and mouse ∆Ecad female tumours showed a YAP1 signature that was absent in ∆Ecad male or Ecad tumours." (PMID 40500450, 2025).
leukemia (12 papers, 2017 to 2025). A malignant (clonal) hematologic disorder, involving hematopoietic stem cells and characterized by the presence of primitive or atypical myeloid or lymphoid cells in the bone marrow and the blood. "In leukemia, lymphoma, and multiple myeloma, low YAP1 levels block apoptosis, while YAP1 activation causes the death of hematologic cancer cells." (PMID 40573272, 2025). "Based on our MSC data, tumorigenesis driven by CDH6/YAP1/OCT4 interactions in DR MSCs may be similar to leukemia, causing blockage of cell differentiation in various stages of hematological development [[." (PMID 35356283, 2022). "USP10 can deubiquitinate and stabilize YAP1, and its inhibitor Wu-5 was found to potently suppress leukemia, exhibiting its potential for eliminating undruggable oncoproteins to restore immunosurveillance." (PMID 38715050, 2024). "It is well known that YAP1 plays a pivotal role in the pathogenesis and progression of cancers, including leukemia." (PMID 35656547, 2022). "However, no reports have been published regarding the role of HDACs in the regulation of YAP1 in leukemia." (PMID 35656547, 2022). "Moreover, YAP1 activation triggers apoptosis specifically in hematological malignancies, including lymphomas, leukemias, and multiple myeloma." (PMID 32422910, 2020). "Finally, we studied the relationship between miR-375 and YAP1 in leukemia cells." (PMID 37397256, 2023). "Our study suggests that YAP1 overexpression could block MSC differentiation and lead to tumorigenesis with a mechanism similar to leukemia formation due to blockage of HSC differentiation [." (PMID 35356283, 2022). "Using T-leukemia NSG mouse model, we found that CD1a CAR-T cells effectively destroyed YAP1-KO T leukemic cells, but not the control leukemic cells, leading to the prolonged survival of the mice; however, this killing process was abrogated by Lat-A treatment." (PMID 38360940, 2024). "Oncogenes (YAP1, Survivin) were shown to be repressed and TSGs (p21, PTEN, CASP1) upregulated under IRF8 overexpression in renal cancer, and negative feedback occurred between IRF8 and β-catenin in leukemia." (PMID 28388578, 2017).
osteoporosis (12 papers, 2020 to 2026). A condition of reduced bone mass, with decreased cortical thickness and a decrease in the number and size of the trabeculae of cancellous bone (but normal chemical composition), resulting in increased fracture incidence. "A study on osteoporosis showed that the transcription factor YAP1 directly binds to and upregulates GPX4 transcriptional activity, thereby inhibiting osteoblast ferroptosis and promoting bone formation." (PMID 41480314, 2025). "Our findings suggest that metformin holds promise as a therapeutic agent for osteoporosis by enhancing type H vessel formation through the inhibition of the YAP1/TAZ-HIF1α axis." (PMID 40159493, 2025). "BMSC-derived extracellular vesicles alleviate mouse osteoporosis via USP7-mediated YAP1 stability and Wnt/β-catenin pathway modulation." (PMID 38399333, 2024). "The use of conditional knockout mice will help to further clarify the crosstalk between inflammation and YAP1/β-catenin signaling in the context of osteoporosis." (PMID 37884520, 2023). "Huang observed for the first time that circ_0024097 promoted osteogenic differentiation via the miR-376b-3p/YAP1 axis and Wnt/β-catenin pathway, thus reducing osteoporosis." (PMID 36879309, 2023). "Future works need to focus on the validation of circ_0001795/miR-339-5p/YAP1 axis in osteogenic differentiation in the animal model of osteoporosis." (PMID 35040370, 2022). "In conclusion, circ-ITCH upregulated YAP1 expression to promote osteogenic differentiation in osteoporosis via sponging miR-214." (PMID 33795657, 2021). "In conclusion, the current findings provided evidences that circ-ITCH promoted osteogenic differentiation and alleviated symptoms of osteoporosis in the OVX mice model by sponging miR-214 to upregulate YAP1 expression." (PMID 33795657, 2021). "We demonstrated that overexpression of circ-ITCH effectively promoted hBMSCs osteogenic differentiation and prevented osteoporosis in the OVX mice model by targeting the miR-214/YAP1 axis." (PMID 33795657, 2021). "In this study, we found YAP1 expression was downregulated in osteoporosis specimens and upregulated in hBMSCs during osteogenic differentiation." (PMID 33795657, 2021). "In the ovariectomized osteoporosis nude mouse model, YAP1 can mediate the therapeutic effect of melatonin toward OP, while the YAP1 inhibitor VP can attenuate the therapeutic effect of melatonin against OP." (PMID 33178690, 2020). "We hypothesized that metformin ameliorates osteoporosis by enhancing HIF1α signaling-induced bone angiogenesis via inhibiting YAP1/TAZ expression." (PMID 40159493, 2025). "Indeed, circRNA_0001795 has been reported to negatively regulate hsa-miRNA-339-5p in BMSCs isolated from osteoporosis, in order to prevent disease progression via YAP1 positive regulation." (PMID 38164139, 2024). "Notably, a study aimed at evaluating the circRNA-mediated pathogenesis of osteoporosis documented that YAP1 is a downstream gene under a circRNA/miRNA axis regulation." (PMID 38164139, 2024). "In summary, IL-11 can induce osteoclast formation through Jak/STAT pathway, MAPK/PI3K pathway, phosphorylation of Yes-associated protein 1 (YAP1) and RANKL-independent mechanism, and is associated with rheumatoid arthritis, femoral arthritis, osteoporosis and other bone diseases." (PMID 38352248, 2023). "Therefore, we focus on the interaction between miR-214 and YAP1 in hBMSCs osteogenic differentiation in osteoporosis." (PMID 33795657, 2021). "However, the function of YAP1 on the osteogenic differentiation of hBMSCs in osteoporosis remains further investigated." (PMID 33795657, 2021). "Indeed, YAP1 is involved in orthopedic degenerative diseases such as osteoporosis (OP) in addition to OA." (PMID 33178690, 2020).
osteoporosis (continued). "Other factors such as Yes-associated protein 1 (YAP1)/Transcriptional activator with PDZ domain (TAZ) or hypoxia-inducible factor 1α (HIF1α), reported to affect type H vessel formation, may also be potential targets for preventing and treating osteoporosis." (PMID 40159493, 2025).
esophageal adenocarcinoma (11 papers, 2014 to 2025). A malignant tumor with glandular differentiation arising predominantly from Barrett mucosa in the lower third of the esophagus. "JQ1 effectively inhibited YAP1 expression and transcription in human esophageal adenocarcinoma cells." (PMID 35601153, 2022). "In the previous study, we also discovered a positive regulation and feedback between PVT1 and YAP1 in esophageal adenocarcinoma, which is involved in tumor development, growth, and homeostasis." (PMID 33076512, 2020). "Furthermore, CA3 in combination with 5-FU inhibited the growth of esophageal adenocarcinoma, especially in YAP1 overexpressing cancer cells." (PMID 33665161, 2020). "CA3 can reduce the expression of YAP1 and weaken the transcriptional activity of YAP1 in a dose‐dependent way, thus significantly hindering the proliferation and differentiation of cancer stem cells and reducing the volume of tumors in the transplanted tumor model of esophageal adenocarcinoma mice." (PMID 37576865, 2023). "The findings manifested that CA3 can represent a new inhibitor of YAP1 to significantly inhibit YAP1/TEAD transcriptional activity, targeting radiation-resistant esophageal adenocarcinoma cells with CSC characteristics." (PMID 38561775, 2024). "Eight cancer cell lines and two Barrett’s esophagus (BE) cell lines were immunoblotted for the expression of CSC- related genes SOX9, YAP1 and Shh." (PMID 24859412, 2014). "Research focused on Barrett’s esophagus and esophageal adenocarcinoma have also suggested that BIRC2, BIRC3, MMP12, MYC, PVT1, and YAP1 may be ecDNA-related oncogenes." (PMID 40569942, 2025).
gastric adenocarcinoma (11 papers, 2015 to 2024). "Deregulation of Hippo kinases is associated with tumorigenicity including gastric adenocarcinoma through hyperactivation of YAP1/TAZ." (PMID 30934860, 2019). "For example, the high expression of YAP1 in advanced gastric adenocarcinoma endows tumors with strong invasion and metastasis ability, thus leading to the occurrence of peritoneal cancer in 45% of gastric adenocarcinoma patients." (PMID 35912206, 2022). "YAP1 was expressed at significantly higher levels in stomach adenocarcinoma (STAD) than in normal gastric mucosa." (PMID 31145543, 2019). "Compared with normal gastric mucosa, YAP1 expression was significantly up-regulated in moderately differentiated gastric adenocarcinoma, poorly differentiated adenocarcinoma, and signet ring cell cancer." (PMID 27835600, 2016). "In summary, we show that Nodal and YAP1 are increased in gastric adenocarcinomas compared to normal tissue." (PMID 27325246, 2016). "We first examined mRNA and protein expression of Nodal and YAP1 in a panel of gastric adenocarcinoma patient samples and matched normal tissue." (PMID 27325246, 2016). "Thus, we here review the recent studies and try to depict how YAP1 senses and responds to the mechanical signals and its potential role in cytoskeleton remodeling in solid tumors including gastric adenocarcinoma." (PMID 30934860, 2019). "Most notably, the data we present here do not address the reason why gastric adenocarcinomas expressing both Nodal and YAP1 at high levels have the worse overall prognosis." (PMID 27325246, 2016). "Despite this, to date, potential roles for Nodal and YAP1 have not been reported in gastric adenocarcinoma (GAC)." (PMID 27325246, 2016).
renal cell carcinoma (11 papers, 2019 to 2025). "In addition, we find that YAP1 nuclear localization is markedly elevated in renal cell carcinoma (RCC), along with its association with HIF1α; this is significant, because VHL is often mutated and is a well-known tumor suppressor in RCC." (PMID 35937460, 2022). "In contrast, the overexpression of YAP1 was associated with the pathogenesis of mucinous tubular spindle cell carcinoma (MTSCC), a rare subtype of renal cell carcinoma." (PMID 37190141, 2023). "Nevertheless, although prior studies have elucidated the pathological roles of YAP1 in tubular or mesangial injuries, renal fibrosis, and even renal cell carcinoma, the physiological functions of YAP1 within the kidney, particularly in the context of DKD, remain largely undetermined." (PMID 39608245, 2024). "In human cells, ARRDC1 and ARRDC3 were shown to induce degradation of the mammalian homolog of Yki, YAP1, by recruiting the E3 ubiquitin ligase ITCH in renal cell carcinoma, suggesting functional homology between human and Drosophila." (PMID 38270169, 2024). "YAP1–HIF1α interaction was higher in NSCLC and renal cell carcinoma samples, indicating a role for this interaction in the genesis of these cancers." (PMID 35937460, 2022).
atherosclerosis (10 papers, 2021 to 2025). A disease characterized by the build-up of fatty material and calcium deposition in the arterial wall resulting in partial or complete occlusion of the arterial lumen. "YAP1 contributed to various of vascular diseases, such as atherosclerosis, hypertension, vascular injury, angiogenesis and aneurysm." (PMID 39495769, 2024). "As an important transcription factor of Hippo pathway, YAP1 is regarded as a new light for the onset mechanism of various diseases, such as cancer, atherosclerosis, fibrosis, and inflammation." (PMID 36182901, 2022). "This is important since Yap1 is also considered a pathological marker in various inflammatory diseases, including atherosclerosis (e.g., Yap1 suppression is connected to NLRP3 inflammasome inhibition) and osseotendinous inflammation (e.g., Yap/Hippo pathway is linked to excessive tenascin)." (PMID 40583463, 2025). "YAP1, which is an important transcription factor in the Hippo pathway, has been studied extensively and regarded as a potential approach for the onset mechanism of various diseases, such as cancer, atherosclerosis, fibrosis, and inflammation." (PMID 35979359, 2022). "Subsequent functional annotation identified eight atherosclerosis-relevant candidate genes: transcription factors (KLF12, KLF6, KLF9, and MEF2C), epigenetic regulators (HDAC9), and signaling molecules (YAP1, SOCS6, and CDC25A)." (PMID 41373654, 2025). "Although SENP3 has been implicated in cancer and metabolic disease through its deSUMOylation of substrates such as β-catenin, YAP1 and CTH, its potential role in atherosclerosis and VSMC phenotypic modulation has not been examined." (PMID 41307849, 2025). "Although prior studies have implicated SENP3 in cancer and metabolic cardiovascular diseases through substrates such as β-catenin, YAP1 and CTH, its role in atherosclerosis has not been explored." (PMID 41307849, 2025).
coloboma (10 papers, 2015 to 2026). An abnormality in which a part of a structure in one or both eyes is missing. "Heterozygous‐dominant YAP1 variants cause developmental eye disorders, including microphthalmia and coloboma." (PMID 36656098, 2023). "A heterozygous loss-of-function mutation in YAP1 has been reported in individuals from a family with isolated ocular coloboma, microphthalmia and/or coloboma." (PMID 31475147, 2019). "Nonsense YAP1 mutations have been shown to co-segregate with autosomal dominantly inherited coloboma." (PMID 28801591, 2017). "Therefore, we screened YAP1 for variants in a cohort of 258 undiagnosed UK patients with developmental eye disorders, including anophthalmia, microphthalmia and coloboma." (PMID 28801591, 2017). "As microphthalmia and coloboma are due to aberrations during eye development, we examined YAP1 expression in human embryonic brain and eye." (PMID 28801591, 2017). "A different nonsense mutation in YAP1 was reported in another family with coloboma as well as non-ocular abnormalities, including hearing loss, intellectual disability, hematuria, and orofacial clefting." (PMID 31475147, 2019).
fibrosis (10 papers, 2019 to 2025). the formation of excess fibrous connective tissue in an organ or tissue in a reparative or reactive process. "It is important to mention that by classifying NASH patients into low F1 and F2 fibrosis grades and high F3 and F4 fibrosis grades, C allele carriers in YAP1 rs11225163 lost its significant association with HCC development in NASH." (PMID 32283835, 2020). "We demonstrated that NAP1L1 is a profibrotic factor that inhibits YAP1 ubiquitination and degradation to regulate cardiac fibrosis." (PMID 37593048, 2023). "Previous studies confirmed YAP1 to be a mechano-transducing effector that translocates from the cytoplasm to the nucleus when cells are shifted from soft to stiff matrices, consistent with our findings studying rat model fibrosis and cirrhosis." (PMID 33763375, 2021). "Fatty acids may promote hepatic fibrosis by activating the transcriptional coactivator YAP1." (PMID 36920600, 2023). "However, the administration of baricitinib markedly reduced plasma ALT (p < 0.05), CK-18 (p < 0.001), and MDA (p < 0.05) levels, as well as hepatic TGF-β (p < 0.05), YAP1 (p < 0.05), and MDA (p < 0.001) levels, in the MTX-induced fibrosis group." (PMID 40428815, 2025). "These mice developed severe, YAP1/TAZ-dependent pancreatic fibrosis and inflammation at a strikingly fast speed that has not been seen in other mouse models." (PMID 31513574, 2019).
lung squamous cell carcinoma (10 papers, 2020 to 2025). "Earlier studies have indicated that the amplification of YAP1 and WWTR1, which encode YAP and TAZ, respectively, has been observed in 16% of lung squamous cell carcinoma." (PMID 38499647, 2024). "Our group previously demonstrated the contribution of YAP1 to the maintenance of CSC activities in FGFR1-amplified lung squamous cell cancer." (PMID 32863772, 2020). "The higher levels of LINC00519 in lung squamous cell carcinoma are associated with a worse outlook for patients, and research has also shown that LINC00519 may speed up the progression of the disease by interacting with miR-450b-5p and miR-515-5p, and by regulating a protein called YAP1." (PMID 40299524, 2025). "LINC00519 was overexpressed and related to a poor prognosis in lung squamous cell carcinoma (LUSC) patients, which promoted tumor progression via miR-450b-5p/miR-515-5p/YAP1 pathway." (PMID 35873495, 2022).